MMP9 (matrix metallopeptidase 9)
Diseases named in the same sentence as MMP9 in open-access papers (continued):
Sharing a sentence is not in itself a finding about the gene and the disease.
tumor (continued). "Drawing an analogy with tumor cell invasion, we hypothesize that interactions between LH and MMP-9 play an important role in neutrophil invasion." (PMID 35203523, 2022). "As well, lycopene attenuated the level of MMP-9 in tumor-bearing mice." (PMID 35990343, 2022). "NET-associated NE and MMP9 cleave laminin and degrade thrombospondin-1 leading to the activation of integrin α3β1 and FAK/ERK/MLCK/YAP signaling, resulting in reactivation of dormant cancer cells during tumor metastasis." (PMID 35574410, 2022). "MMP-2 and MMP-9 are most closely related to tumor invasion and metastasis." (PMID 36142286, 2022). "Overexpression of MMP-2 and MMP-9 can enhance the invasion and migration of tumor cells." (PMID 35220896, 2022). "In addition, MMP1, MMP2 and MMP9, which are closely related to tumor cell migration, were significantly upregulated in the GDF10‐treated group." (PMID 33657265, 2022). "It is known that MMP1, MMP9, and Twist participate in tumor invasion, metastasis, and VM formation." (PMID 35321317, 2022). "In brief, MMP-2 and MMP-9 proteins are two crucial facilitators that are conducive to potentiating tumor metastatic and invasive potentials, these therapeutic candidate agents are expected to be used to the clinic CRC treatment and intervention by targeting the two crucial targets." (PMID 35308223, 2022). "Previous study has shown that MMP-2 and MMP-9 play important roles in tumor invasion and migration." (PMID 35220896, 2022). "Caffeic acid also increased mRNA levels of TIMP-1 and TIMP2 (tissue inhibitors of metalloproteinases 1 and 2), and decreased mRNA levels of VEGFA (vascular endothelial growth factor A), metalloproteinases MMP-2, and MMP-9, essential for aggressive tumor growth and metastases." (PMID 36614030, 2022). "Evidence from oncology studies suggests that activation of the MAPK/Erk signaling pathway could elevate the expression of MMP-2 and MMP-9 in different tumor cells, thereby enhancing their proliferation and invasion and metastasis." (PMID 36345403, 2022). "Moreover, an anti-MMP9 antibody significantly reduced ascites and the tumor burden in the pancreas and improved the progression-free survival (PFS) in patients treated with NPT + GEM." (PMID 35406619, 2022). "Our studies show that the effect of GNP on tumor cells metastasis may closely relate to the regulation of GNP on MMP-9." (PMID 35954126, 2022). "KNTC1 has been speculated to facilitate tumor cell migration and invasion by regulating MMP9 and MMP2." (PMID 35389773, 2022). "A study showed that the inhibition of TGF-β increases the proliferation and matrix metallopeptidase 9 (MMP-9) expression of tumor-associated fibroblasts (TAF), which negatively regulate PD-L1 expression on the surface of tumor cells and reduce anti-PD-1 efficacy." (PMID 35833121, 2022). "Moreover, the impact of expression and methylation status of LCN2, SLC22A17, and MMP9 on overall survival and progression free interval was tumor type–dependent." (PMID 36211450, 2022). "Finally, the correlation analysis between genes and isoforms of LCN2, SLC22A17, and MMP9 in both normal and tumor samples was performed to detect any interaction between the three genes, including the relative isoforms." (PMID 36211450, 2022). "Studies have indicated that PI3K/AKT signaling axis activation could activate AP-1 and induce the expression of MMP-9, ultimately promoting tumor cell proliferation, invasion, and migration." (PMID 36247874, 2022). "Kahweol may inhibit the phosphorylation of JNK1/2 and p38 MAPK and the activation of NF- κ B to reduce the expression of phorbol 12-myristate 13-acetate (PMA)-enhanced matrix metalloproteinase-9 (MMP-9) to promote an anti-tumor effect." (PMID 35889800, 2022). "Among them, MMP2 and MMP9 could degrade type IV collagen, elastin, gelatin and other components, directly destroy the extracellular matrix barrier and promote tumor metastasis." (PMID 35332127, 2022).
tumor (continued). "Importantly, it has been revealed that MMP-2 expression is positively controlled by Smad2 whilst MMP-9 is modulated via NF-κB p65/p50 transcription signaling in tumor tissues and cells of CRC." (PMID 35308223, 2022). "MMP-9 is a protease with a key role in tumor progression and metastasis." (PMID 35220878, 2022). "Finally, we observed that the presurgical plasma MMP9 level was significantly correlated with MMP9 mRNA tumor expression (p = 0.033)." (PMID 34980260, 2022). "As a protease, MMP-9 influences the tumor stromal remodeling and might be involved in the breakdown of the basement membrane." (PMID 36242015, 2022). "Furthermore, NDRG2 suppresses tumor invasion by attenuating matrix metalloproteinase 9 (MMP9) expression via NF-κB inhibition." (PMID 36012631, 2022). "The enzyme activities of MMP-2 and MMP-9 in the plasma of the tumor control group were set at 100%." (PMID 35711540, 2022). "Finally, we calculated the tumor mutation burden (TMB) of 33 cancer types and analyzed the correlation between MMP-9 and TMB, DNA microsatellite instability, and DNA repair genes." (PMID 35178444, 2022). "Next, we measured the expression of MMP2 and MMP9 in tumor tissues." (PMID 36003306, 2022). "Other authors have also shown overexpression of MMP9 in tumor tissue." (PMID 36139645, 2022). "Moreover, about 0.6-fold increased MMP9 activity was detected in ACHN-G6PDOE-derived tumor tissues compared with the control, whereas the MMP9 activity was decreased by about 35% in Caki-1-G6PDSi-derived tumor tissues." (PMID 34975298, 2022). "Thus, 125I seed implantation inhibits tumor invasion by changing the expression levels of vimentin, N-cadherin, and MMP-9 and induces the apoptosis of NSCLC cells via its effect on the mitochondrial pathway." (PMID 35692770, 2022). "Since we also found a positive correlation between MMP-9 and the percentage of tumor cells, it is tempting to speculate that MMP-9 created a positive feedback, activating neutrophils to release NETs, and thereby favoring tumor progression." (PMID 35626131, 2022). "↑ uPA 93% of PDAC tissue. ↑ uPA, ↑ uPAR or ↑ MMP-9 associated with ↓ OS versus non-expression. ↑ uPA mRNA present in cytoplasm of tumour cells and adjacent pancreatic ducts." (PMID 35204653, 2022). "Moreover, in vivo animal experiments further confirm that PEG/ZIF-8@HF shows anti-tumor effect by up-regulating the pro-apoptotic proteins caspase-3 and caspase-8, and down-regulating the migration-promoting invasion protein MMP-9." (PMID 35373691, 2022). "In addition, MMP2 and MMP9 released by MCs can promote angiogenesis and tumor invasiveness, respectively." (PMID 36591235, 2022). "Furthermore, TANs-derived MMPs, especially MMP-9, enhance tumor angiogenesis and tumor cell infiltration." (PMID 36741415, 2022). "Therefore, we assessed the effect of cordycepin on the expression of EMT-related proteins (N-cadherin, E-cadherin, snail, and ZEB1) and matrix metalloproteinases (MMP2 and MMP9) in tumor tissues by immunohistochemistry and Western blotting." (PMID 36142286, 2022). "Furthermore, it was also noted that overexpression of MMP9 expedited tumor growth and generated a considerable increase in clonogenic capacity." (PMID 35884733, 2022). "Matrix metalloproteinases MMP-2 and MMP-9 are key regulators of tumor invasion and metastasis." (PMID 36079127, 2022). "This study provides an overview on the epigenetic regulation of LCN2, SLC22A17, and MMP9 in the major tumor types allowing the identification of novel DNA methylation biomarkers and potential epi-drug targets of TME involved in tumor progression and drug resistance." (PMID 36211450, 2022). "In addition, IHC staining results revealed that the E2F5, Ki67, and MMP9 positive cells were markedly reduced in the tumor tissues of the sh-circFOXM1 group." (PMID 34784267, 2022).
tumor (continued). "The downregulation of FAK expression can lead to changes in a wide range of signal-regulated proteins that are related to tumor invasion and migration, such as the downregulation of MMP-9 activity in the extracellular matrix, PI3K/Akt/NF-κB signal pathway inhibition, and F-actin depolymerization." (PMID 36686732, 2022). "In addition, MMP-9 maintains the integrity of epithelial mucosa and acts as a tumor suppressor in CAC, which is inseparable from its function of mediating the level of proinflammatory cytokines." (PMID 36776395, 2022). "Alteration in PCa cell aggressiveness was also observed in both cell lines after PPAT explant co-culture, demonstrated by a significant increase in expression levels of genes implicated in tumor cell proliferation (ESRRA) and in tumor invasive and metastatic potential (MMP-9, TWIST1)." (PMID 35978404, 2022). "Therefore, MMP9 is able to reduce the chemotactic abilities of selected chemokines and hence inhibit the immune cell trafficking and tumor tissue infiltration." (PMID 35406619, 2022). "Also, western blot assay exhibited that circ_0005576 absence was able to apparently repress the expression of vimentin and MMP9 in the mice tumor tissues." (PMID 35378711, 2022). "GNP has great potential as MMP-9 inhibitor and could be developed as a functional food or drug to prevent tumor metastasis." (PMID 35954126, 2022). "This complex downregulates the expression of IL-8 and MMP-9 and elevates the expression levels of Notch 4, Ikaros, and integrin alpha-D/CD-11d (tumor-suppressive), which conjointly prevents inflammation, metastasis, and epithelial-mesenchymal transition (EMT) in CML cells." (PMID 35815090, 2022). "The increased expression of TNF-α, TGF-β, MMP-2, and MMP-9 might explain how the P. gingivalis LPS exerts pro-tumor effects." (PMID 36552854, 2022). "In the xenograft tumours, compared with the siNC control group, HBx‐expression and knockdown of B56γ in the si2R5C group upregulated the expression of p‐AKTThr308/Ser473 and tumour metastasis‐associated MMP2 and MMP9." (PMID 35811356, 2022). "Decreased tumor cell viability and proliferation, as well as collagen I-mediated cell adhesion and the action of MMP-2 and MMP-9, enzymes that play an important role in the degradation of the extracellular matrix and promote tumor invasion and metastasis, have been reported." (PMID 35563133, 2022). "It was also reported that activation of STAT3 could promote the expression of MMP2 and MMP9 in tumor cells, thus upregulate their ability of invasion and metastasis." (PMID 36188592, 2022). "Our data show that MMP-9, a matrix metallopeptidase previously shown to be involved in tumor vascularization and metastasis is decreased eightfold in the presence of SSO55 and reduced to near undetectable levels in the presence of both SSO55 and IGF-1R-blocking antibody." (PMID 35017650, 2022). "Moreover, gelatine zymography confirmed the expression of pro-active MMP-2 (9/9) and MMP-9 (9/9) and, most importantly, indicated the presence and increased activity of their active forms (82 and 62 kDa, respectively) in tumour samples." (PMID 36518899, 2022). "In particular, CCL5 has been shown to support the αvβ3 integrin-mediated tumor cell migration through activation of the PI3K/AKT and NF-kB signaling pathways, and by increasing the production of matrix metallopeptidases 2 (MMP-2) and MMP-9, able to promote tumor cell invasiveness." (PMID 36428727, 2022). "MMP2 and MMP9 are considered to exert an important role in tumor metastasis." (PMID 35912155, 2022). "Genetic IL-25 deficiency led to a reduction in tumour Mmp9 expression in AOM/DSS mice, indicating that IL-25 may induce MMP9 expression in CRC." (PMID 36263033, 2022). "MMP-9 plays an important role in the process of tumor development, especially in tumor metastasis." (PMID 35954126, 2022).
tumor (continued). "Interestingly, the expression of both LNC2 and MMP9 genes was increased in 16 tumor types, demonstrating their involvement in tumor development." (PMID 36211450, 2022). "The expressions of RECK and MMP9 were associated with tumor staging and grading, with a significant negative relationship between them." (PMID 35562926, 2022). "In particular, this study showed that MMP-9 promotes an anti-tumor immune response by inducing neutrophil infiltration and activating tumor-infiltrating macrophages, suggesting that the anti-tumor activity of MMP-9 is mediated by its modulation of the innate immune response." (PMID 36741729, 2022). "Indeed, active MMP-9 expression can occur in up to 73% of EGFR amplified tumours and is strongly correlated with EGFRvIII expression, with MMP-9 expression occurring in up to 83% of EGFRvIII-expressing tumours." (PMID 36497413, 2022). "In addition, MMP‐2, MMP‐7 and MMP‐9, the target genes of Wnt/β‐catenin signaling, function to degrade extracellular matrix and basement membrane to promote tumor cell metastasis." (PMID 34165914, 2021). "Moreover, we designed MMP-9 protease recognition motifs into the linker region for tumor-specific cleavage of the fusion and release of the masking unit." (PMID 34413859, 2021). "Inhibition of metastatic signaling through the downregulation of BMP-7 and MMP-9 expression may interrupt bone–tumor communication." (PMID 34440874, 2021). "MMP-9 expression is considered a major prerequisite for tumor invasion." (PMID 34769032, 2021). "Previous reports indicated that MMP-2 and MMP-9 were related to tumor invasion and metastasis." (PMID 34685504, 2021). "The active MMP7 can also cleave the pro-MMP2 and pro-MMP9 to facilitate tumor invasion." (PMID 33936204, 2021). "For example, NET-derived NE and MMP-9 degraded ECM to actively induce tumor invasion." (PMID 34503307, 2021). "Upregulation of MMP9 and IL-6 promotes tumour invasion, proliferation, apoptosis and metastasis." (PMID 33984826, 2021). "Besides cytokines and chemokines, VEGF and MMP-9 secreted by TANs are known to mediate the process of tumor angiogenesis." (PMID 34201758, 2021). "Finally, in hepatocellular carcinoma, EVs derived from M2 TAMs transfer αMβ2 to the tumor cells to activate MMP-9." (PMID 34943937, 2021). "MMP-9 destroys the basement membrane and promotes tumor invasion and metastasis by enzymolysis." (PMID 33854560, 2021). "Furthermore, Curcumin also reduces CCL2‐mediated MMP9 expression that contributes to tumour progression." (PMID 34464477, 2021). "Lycopene supplementation (1, 20 mg/kg BW; 2 times per week for 12 weeks) in nude mice injected with SK-Hep-1 cells managed to significantly reduce MMP-2, VEGF, PCNA, MMP-9, suppress tumor metastasis, mean number of tumors, tumor cross-sectional area while increase nm23-H1." (PMID 34202203, 2021). "Likewise, MMP-9 has been suggested to promote tumour tissue vascularization via vascular endothelial growth factor (VEGF) mobilization and our study showed that tested complexes alleviated the expression of VEGF in tumour cells." (PMID 33670389, 2021). "Likewise, increased expression of IL1A (log2 fold change = −4.15) and TGFA (log2 fold change = −2.28) was observed in the HCC tumor cells leading to increased expression of TME-derived MMP9 and MMP2, respectively." (PMID 33995488, 2021). "Therefore, MMP-2 and MMP-9 are considered as potential biomarkers for the process of tumor development and are important potential targets for antitumor therapy." (PMID 33959183, 2021). "In BCa, MMP-9 has a positive correlation with tumor progression and invasion." (PMID 34122670, 2021). "MMP9 is a key factor in the process of tumor invasion and metastasis." (PMID 33430865, 2021). "MMP9 plays a critical role in the process of tumor invasion and progression." (PMID 33919449, 2021).
tumor (continued). "The addition of stromal cells increased transcription of matrix remodelling proteins FN1 and MMP9, induced release of tumour-promoting immune molecules MIF, Serpin E1, CXCL1, IL-8 and CXCL12 and altered cancer cell expression of immunotherapeutic targets EGFR, CD47 and PD-L1." (PMID 34885111, 2021). "Similarly, the enzyme-cleavable zwitterionic stealth peptide that consisted of MMP-9 cleavable cell-penetrating Tat sequences was applied to coat gold nanorods for controllable tumor therapy." (PMID 34201333, 2021). "In melanoma and lung and prostate tumors, targeting recruitment of MDSCs by inhibiting CSF-1 receptor inhibits tumor angiogenesis associated with reduced expression of proangiogenic genes such as VEGF-A and MMP-9 and reverses tumor resistance to antiangiogenic therapy." (PMID 35003065, 2021). "Carcinoma-associated fibroblasts (CAFs), often known as activated fibroblasts, are generally derived from the tissue-resident normal fibroblasts (NFs) and can promote tumor angiogenesis by secreting higher levels of proteolytic enzymes, such as matrix metalloproteinase 9 (MMP9)." (PMID 34327132, 2021). "At first sight this may appear paradoxical as Mmp9 and Bv8 overexpression due to stromal JUNB loss should also have a positive impact on primary tumor growth." (PMID 34282521, 2021). "The previous report showed that high expression of MMP9 could promote metastasis of tumor cells, promotes tumor angiogenesis, and inhibits apoptosis." (PMID 35201491, 2021). "A trending decline in MMP-9 in MDA-MB-231 cells may limit tumor cell migration and adhesion to bone as well as decrease osteoclast differentiation and activation." (PMID 34440874, 2021). "On the one hand, MMP9 facilitates tumor migration and angiogenesis by promoting ECM degradation." (PMID 34607974, 2021). "MMP2 and MMP9 degrade type IV collagen in basement membranes, increasing tumor aggressiveness." (PMID 34830271, 2021). "Recently, a study showed that Lut inhibits the metastasis of ovarian cancer cells (A2780 cells) by downregulating the expression of MMP-2 and MMP-9 both in vitro (A2780 cells) and in vivo in a tumor model comprising subcutaneous injection of A2780 cells in nude mice." (PMID 33498927, 2021). "Transforming growth factor (TGF)‐β signalling plays an important role at the early stage of EMT programme in HCC development and MMP9 is a key target of the tumour‐progressive TGF‐β signalling, which might be a potential target for HCC therapy." (PMID 33215860, 2021). "Moreover, the expression of matrix metalloproteinase-9 (MMP-9) in the tumor tissue has a close relationship with tumor invasion and metastasis." (PMID 34162396, 2021). "Since NF-κB/MMP-9/VEGF pathway play pivotal roles in tumor angiogenesis and metastasis." (PMID 34059099, 2021). "In addition, the invasion of tumor cells to local tissues requires the remodeling of extracellular matrix by proteases such as MMP9." (PMID 34516317, 2021). "Further studies uncovered that MMP9 and IGFBP1 were associated with tumor immune and progression." (PMID 33758602, 2021). "It is tempting to speculate that FQ-induced cAMP may contribute to the inhibition of MMP-9 production and motility in malignant tumor cells." (PMID 34769032, 2021). "Tumor markers (CEA, CYFRA 21-1, and NSE) were measured in the patients’ sera and plasmas, along with IL-6, TNF-α, SAA1, CRP, MMP-2, MMP-9, glucose, lactate, and LDH, utilizing enzyme-linked immunosorbent assays, enzyme immunoassays, and automated clinical chemistry and turbidimetry systems." (PMID 34439874, 2021). "However, a number of tumorigenic proteins like Bcl family, Mcl-1, survivin, IAP-1/2, COX-2, cyclin D1, VEGF, and MMP-9 can negate the apoptotic influence and promote tumor cell survival." (PMID 34360911, 2021).